SNORA4 (small nucleolar RNA, H/ACA box 4)
Synonyms: ACA4
Gene: Small nucleolar RNA gene on chromosome 3 (186,787,612 to 186,787,749, forward strand). Ensembl gene ENSG00000263776.
Gene Ontology:
Biological process: RNA processing
Cellular component: nucleolus
Homologues: Orthologues: chimpanzee SNORA4 (100% identical), macaque SNORA4 (98% identical), rabbit SNORA4 (90% identical), pig SNORA4 (86% identical), mouse Gm24616 (85% identical), rat Snora4 (80% identical).
Diseases named in the same sentence as SNORA4 in open-access papers:
SNORA4 is named in the same sentence as 3 diseases in open-access papers, as found by Europe PMC text mining. Sharing a sentence is not in itself a finding about the gene and the disease.
SNORA4 shares sentences with these, for which no sentence is quoted: Autoimmunity (1 paper); cancer (1); infarction (1).